ATE1 (arginyltransferase 1)
Diseases named in the same sentence as ATE1 in open-access papers (continued):
Sharing a sentence is not in itself a finding about the gene and the disease.
infection (3 papers, 2016 to 2023). The state of being infected such as from the introduction of a foreign agent such as serum, vaccine, antigenic substance or organism. "Once the increased abundance of ATE1 in the infection was confirmed, a multicorrelation analysis was performed using omic data to verify which proteins correlated with ATE1, and which pathways could be associated with this increased abundance." (PMID 36851505, 2023). "Together with the apparent susceptibility of ate1 ate2 plants to natural pathogen infection, these results led us to systematically test whether the Arg/N-end rule is indeed involved in controlling plant-pathogen interactions." (PMID 27173012, 2016). "ATE1 expression was higher during infection in most of the datasets, significantly upregulated at both transcript and protein levels." (PMID 36851505, 2023). "Time course data revealed an increase in ATE1 after 2 h of infection in Vero CCL-81 cells (p-value = 0.0294)." (PMID 36851505, 2023). "The GBP2 protein, involved in the cellular response to infections, was correlated with ATE1 in four studies." (PMID 36851505, 2023). "Here, we confirm the potential of tannic acid to reduce viral load, and furthermore, to modulate ATE1 levels during infection." (PMID 36851505, 2023). "We then determined the proportion of germinated spores that had produced secondary hyphae at an early stage of infection (2 dpi) and found a low but significant increase for ate1 ate2, prt6-5 and prt1-1 mutants." (PMID 27173012, 2016). "To identify biological pathways that are affected in N-end rule mutants upon pathogen infection, we carried out a transcriptomics experiment following inoculation of wild-type and ate1 ate2 double-mutant plants with Pst AvrRpm1." (PMID 27173012, 2016). "The results of this time-course experiment showed that the onset and the duration of the response to Pst AvrRpm1 infection is similar in wild-type and ate1 ate2 plants, however, the amplitude of the gene expression changes appears to be overall reduced in the double mutant." (PMID 27173012, 2016). "We found that at 7 days post inoculation (dpi), ate1 ate2, prt6-5 and prt1-1 mutants, but not ntaq, exhibited an increase in susceptibility to infection with S. sclerotiorum." (PMID 27173012, 2016). "Thus, it appears that these processes are affected in the ate1 ate2 mutant in response to Pst AvrRpm1 infection." (PMID 27173012, 2016). "The treatment with TAG induced the levels of ATE1, being possible to observe a significant increase in P1 in relation to the CTRL, WT, and P2 groups after 48 h of infection." (PMID 36851505, 2023). "While characterizing a mutant Arabidopsis line for the two paralogous Arg-transferases ATE1 and ATE216, 17, we noticed that these plants often succumbed to natural pathogen infections, while wild-type plants grown under the same conditions remained healthy." (PMID 27173012, 2016).
cardiac diseases (2 papers, 2020 to 2022). "Our data clarify the involvement of ATE1 in case of stress, potentially providing a novel insight for the in vivo functions of ATE1 in case of cardiac diseases." (PMID 31953451, 2020). "The relationship between ATE1 function and heart diseases has been demonstrated in recent years." (PMID 35341136, 2022). "Interestingly, our results indicated another potential involvement of ATE1 in cardiac diseases." (PMID 31953451, 2020).
metabolic disease (1 paper, 2020). A congenital disorder (due to inherited enzyme abnormality) or acquired (due to failure of a metabolically important organ) disorder resulting from an abnormal metabolic process. "Multiple lines of genetic studies have shown an important role of the ATE1 gene (ate1) in the cardiovascular and/or metabolic diseases in animals." (PMID 32435206, 2020).
neurodegenerative disease (1 paper, 2021). A disorder of the central nervous system characterized by gradual and progressive loss of neural tissue and neurologic function. "Intriguingly, high throughput studies from other groups show that Ate1 is significantly reduced in several of these neurodegenerative diseases." (PMID 33931669, 2021).
ATE1 also shares sentences with these, for which no sentence is quoted: alopecia (1 paper); Alzheimer disease (1); asthma (1); cardiomyopathy (1); cardiovascular diseases (1); Hyperkinesia (1); leukemia (1); male infertility (1); mesothelioma (1); Parkinson (1); scoliosis (1); Seizure (1).